MMP2 (matrix metallopeptidase 2)
Diseases named in the same sentence as MMP2 in open-access papers (continued):
Sharing a sentence is not in itself a finding about the gene and the disease.
cancer (continued). "To determine whether MMP-2 or MMP-9 in the astrocyte CM were involved in inducing cancer cell invasion, we IP’d MMP-2, MMP-9 or both in astrocyte CM with specific respective antibodies, and performed an invasion assay with the astrocyte CM depleted of the MMPs." (PMID 24324647, 2013). "Therefore, the generation of highly selective MMP-2 inhibitors could be useful for the treatment of a number of cancers including bone metastases." (PMID 22238668, 2012). "In recent years, the p38 MAPK has emerged as a key signaling molecule in the regulation of cancer invasion and metastasis by modulating the expression and activity of molecules governing the degradation of extracellular matrix (that is, urokinase plasminogen activator, MMP-2, and MMP-9)." (PMID 21167057, 2010). "Therefore, CSE1L regulates MMP-2 secretion and enhances the invasion of cancer cells." (PMID 20701792, 2010). "In addition, we did not observe a significant association between MMP-2 expressed at the border between the epithelial cancer cells and VEGF-A protein." (PMID 19352388, 2009). "MMP, including MMP-2 (gelatinase A) and -9 (gelatinase B), play an important role in tissue remodeling in various physiological and pathological processes, such as implantation, ovarian and uterine functions during peri-partum, wound healing, cancer development etc.." (PMID 19116037, 2008). "This is the case of mmp2 (gelatinase A) that is involved in the breakdown of extracellular matrix in normal physiological processes, such as embryonic development, reproduction, and tissue remodeling, as well as in disease processes such as inflammation and cancer." (PMID 17397547, 2007). "•MMP-2 and MMP-9 Regulation: Knockdown of MEG3 increased MMP-2 and MMP-9 expression, promoting cancer cell invasion." (PMID 41480643, 2026). "In particular, Src–FAK signaling upregulates MMP2 and MT1-MMP, which degrade type IV collagen in the basement membrane, a key barrier to cancer invasion." (PMID 41597235, 2026). "Batimastat was the first MMPI to enter clinical trial for malignant tumours by inhibiting MMP‐1, MMP‐2, MMP‐7 and MMP‐9." (PMID 41546170, 2026). "Elevated MMP-2 and MMP-9 have been consistently correlated with poor outcomes and metastatic progression in ovarian and other cancers, and our observations reinforce this established paradigm." (PMID 41480643, 2026). "Among the 22 investigated MMPs, seven genes (MMP2, MMP3, MMP10, MMP12, MMP14, MMP15, and MMP16) were upregulated in cancer, while MMP8 was downregulated." (PMID 41728806, 2026). "Preventing Cancer Spread: Curcumin lowers the activity of enzymes like MMP-2 and MMP-9, which help cancer cells invade surrounding tissues." (PMID 40649942, 2025). "As previously reported, EFEMP1 reduced the expression of MMP2 and MMP9 by regulating the activity of ERK1/2, thereby inhibiting the migration of cancer cells." (PMID 40316017, 2025). "Matrix metalloproteinase-2 (MMP-2) enhances invasion and metastasis in cancer cells by degrading the extracellular matrix (ECM) and promoting angiogenesis." (PMID 40725394, 2025). "SERPING1, a protease inhibitor belonging to the serpin superfamily, can modulate extracellular matrix metalloproteinases (MMPs) activity, such as MMP‐2 and MMP‐9, to influence cancer cell motility." (PMID 39474998, 2025). "Notable examples—such as ANO1, BAG2, DHCR7, MMP2, and TRAM2 —align with prior studies linking these genes related to cancer proliferation or metastasis in multiple cancer types." (PMID 40361356, 2025). "It disrupts metastasis by inhibiting the activity of matrix metalloproteinases (MMPs), particularly MMP-2 and MMP-9, which degrade the extracellular matrix (ECM) and allow cancer cells to invade surrounding tissues and enter the bloodstream." (PMID 39861761, 2025). "MMP-2 and MMP-9 are particularly significant in cancer metastasis as they primarily degrade gelatin and collagen IV and V, enhancing the invasiveness of cancer cells." (PMID 41356146, 2025).
cancer (continued). "These NPs also inhibit the expression of MMP-2 and MMP-9, enzymes involved in cancer invasion and metastasis." (PMID 39861761, 2025). "Proteomic analysis of mouse plasma revealed increased secretion of cancer-related proteins (CXCL13, CXCL16, and MMP2) in the MCPIP1-mutant group." (PMID 39815326, 2025). "CAFs also secrete MMP-2 and MMP-9 that degrade the ECM to create gaps in the basement membrane and align fibronectin to support cancer cell invasion." (PMID 41429896, 2025). "The suppression of matrix metalloproteinases MMP-2 and MMP-9, enzymes essential for extracellular matrix degradation and cancer cell invasion, has been observed following treatment with aronia polyphenols." (PMID 41515306, 2025). "Analysis of MMP-2 and MMP-9 levels in tissues from radical prostatectomy demonstrated that these metalloproteinases were significant warning signs of cancer recurrence." (PMID 40563423, 2025). "The secretion of MMPs, such as MMP-2, MMP-11 and MMP-14, by these cells accelerates ECM degradation, promoting cancer cell invasion." (PMID 40399946, 2025). "Further analysis was conducted to evaluate the expression of matrix metalloproteinases (MMP-2 and MMP-9), enzymes critical for cancer cell invasion and metastasis." (PMID 39781358, 2025). "Due to the crucial role of MMP-2 and MMP-9 in cancer progression, targeting their regulation has emerged as a promising therapeutic approach." (PMID 40563423, 2025). "This inhibition was associated with a reduction in the expression of matrix metalloproteinases MMP-2 and MMP-9, and proteins related to epithelial–mesenchymal transition (EMT), indicating a broad impact on cancer cell aggressiveness." (PMID 40299445, 2025). "Research has found that ginsenoside CK can effectively inhibit the expression of AKT/mTOR/p70S6K1 proteins in cancer cells, block the PI3K/AKT/mTOR signaling pathway, and reduce the expression of MMP2 and MMP9 proteases." (PMID 40422575, 2025). "This reduction leads to a decreased expression of downstream MMP2 and MMP9 proteases, which helps prevent cancer cell migration and metastasis." (PMID 40422575, 2025). "Among these, MMP-2 and MMP-9 are key proteins that promote cancer cell invasion by degrading type IV collagen, a major component of the basement membrane." (PMID 41471692, 2025). "MMP family members, such as MMP2, MMP8, and MMP9, have important roles in degrading the extracellular matrix (ECM), contributing to migration and metastasis formation in various cancers." (PMID 40566630, 2025). "This activation increases the expression of MMP2/9 proteins, promoting ECM degradation and thereby facilitating cancer cell migration." (PMID 40422575, 2025). "In vitro experiments based on the COAD-derived cancer cell lines SW480 and Caco-2 further confirmed the role of MMP-2 in regulating PD-L1 expression in COAD." (PMID 40611940, 2025). "Repeated high-pressure states result in vascular remodeling, activating enzymes like matrix metalloproteinase-2 (MMP-2), which degrade the extracellular matrix (ECM) and facilitate cancer cell invasion." (PMID 41139205, 2025). "apples, a southern Italian variety, were able to inhibit matrix metalloproteinases (MMP-2 and MMP-9) and EMT, down-regulate Smad signaling (crucial for cancer progression), and decrease levels of NF-κB." (PMID 39859345, 2025). "In this review, understanding how the bioactive compounds in wine influence MMPs, specifically MMP-2 and MMP-9, provides valuable insights into their potential implications for cancer therapy." (PMID 40563423, 2025). "In this review, we summarize and discuss how bioactive molecules in wine regulate MMP-2 and MMP-9 through bioactive compounds derived from wine and explore their implications for cancer treatment." (PMID 40563423, 2025). "Previous studies have shown that halofuginone inhibits MMP-2 and MMP-9 in cancer and liver tissues, while SIS3 reduces TGFβ1-induced MMP activity in HCC1806 cells." (PMID 40535569, 2025).
cancer (continued). "Among these, multiple flavonols in wine have been reported as regulators of MMP-2 and MMP-9, enzymes involved in cancer progression." (PMID 40563423, 2025). "Within the MMP family, MMP‐2 and MMP‐9 are particularly significant, as their release by cancer cells facilitates matrix degradation, thereby promoting infiltration, invasion, and distant metastasis." (PMID 39834553, 2025). "MMP enzymes, such as MMP-2 and MMP-9, promote extracellular matrix (ECM) degradation and basement membrane, thereby facilitating metastasis during the progression of cancer." (PMID 41234632, 2025). "It suppressed the activity and expression of matrix metalloproteinases (MMPs), such as MMP-2 and MMP-9, which are critical for cancer cell invasion." (PMID 40136435, 2025). "An in vitro study conducted on SCC HNC cell lines showed that extracts from Ocinum sanctum leaves can decrease the activity of MMP-2 and MMP-9 metalloproteinases, thus significantly reducing cancer cell invasion (p < 0.05)." (PMID 40282445, 2025). "As a transcription factor, c-Jun regulated the expressions of N-cadherin, E-cadherin, MMP2, MMP9 and TIMP2, which are involved in EMT and regulate migration and invasion of most cancers." (PMID 40149013, 2025). "Analysis of mouse plasma revealed increased secretion of cancer-related proteins, such as CXCL13, CXCL16, MMP2, selectins, and pentraxin 2, in the group with MCPIP1 mutations." (PMID 39815326, 2025). "This was achieved by downregulating the expression of MMP-2, MMP-9, and urokinase-type plasminogen activator (u-PA), key mediators of cancer cell invasion and metastasis." (PMID 40136435, 2025). "FAM129B has been identified as a key factor that promotes cancer cell invasion in non-small-cell lung cancer (NSCLC) by facilitating the phosphorylation of focal adhesion kinase (FAK), which upregulates Matrix metalloproteinase-2 (MMP-2) and Cyclin D1." (PMID 39941813, 2025). "This review provides a focused synthesis of current knowledge regarding the regulatory effects of wine-derived bioactive compounds on MMP-2 and MMP-9 in the context of cancer progression." (PMID 40563423, 2025). "Isorhamnetin suppresses cancer growth and pulmonary metastases by downregulating VEGF and MMP-2 expression while upregulating endostatin, an angiogenesis inhibitor." (PMID 40806510, 2025). "Reduction in RBP4 levels results in inactivation of N-cadherin, MMP2, -3, -9, and an increase in E-cadherin, which also proves the roles of RBP4 in cancer cell migration." (PMID 41007818, 2025). "Our study provides compelling evidence for further investigating MMP-2 as a therapeutic target in COAD, as well as underscoring the potential of combination immunotherapies to improve treatment outcomes in cancer patients." (PMID 40611940, 2025). "Increased interaction between extracellular Hsp90 and Aha1 facilitates activation of matrix metalloproteinase-2 (MMP-2), which increases cancer invasion/metastasis." (PMID 39776493, 2024). "The results showed that MMP2, MMP9, MMP12, and MMP16 promoter regions in KIRC samples were hypomethylated compared to non-cancer samples." (PMID 38560573, 2024). "The urokinase plasminogen activator (uPA) and the MMPs, like MMP-2 and MMP-9, can destroy several ECM components and accelerate the spread and metastasis of cancer." (PMID 38481883, 2024). "Downregulation of p38 MAPK leads to suppressed expression and activity of matrix metalloproteinases MMP-2 and MMP-9, supporting the role of p38 in facilitating cancer cell invasion." (PMID 38806469, 2024). "In fact, MMP2 and MMP14 in the conditioned media of mild aggressive cancer cells were strongly activated by SEMA3F, in accordance with previous results that demonstrated that these MMPs are involved in the cleavage of collagen IV, a basal membrane compound." (PMID 39138514, 2024). "These compounds target key oncogenic pathways, such as those regulated by Bcl-2, HER2, p120, MMP-2, and MMP-9—proteins essential for cancer cell survival and metastasis." (PMID 39840104, 2024).
cancer (continued). "Activation of CAF-derived MMP2 by membrane type I matrix metalloproteinases (MT1-MMPs) contributes to the degradation of nerve bundle collagen and facilitates the diffusion of cancer cells in the perineural space." (PMID 39119085, 2024). "The activation of the MAPK and NF-κB pathways enhances the expression of MMP-2 and MMP-9, thus promoting cell invasion and migration and cancer disease progression." (PMID 39335164, 2024). "In particular, the expression and activity of MMP-2 and MMP-9, also known as gelatinases or type IV collagenases, are correlated with the aggressiveness of cancer and a poor prognosis." (PMID 39335164, 2024). "For example, a study reengineered anthrax toxin, initially developed for human cancers, to target OMM by homing in on markers such as urokinase plasminogen activator (uPA) and metalloproteinases (MMP-2)." (PMID 39408717, 2024). "High concentrations of quercetin significantly decreased MMP-2 and MMP-9 expression, while low concentrations increased it, which, in turn, enhanced the malignant potential of cancer cells." (PMID 39335164, 2024). "In EAC, significant expression of APE1 (apurinic/apyrimidinic endonuclease 1) has been shown to regulate MMP‐14, activating MMP‐2 and leading to redox‐dependent ECM degradation, thus affecting the invasive capacity of cancer cells." (PMID 39415846, 2024). "Dihydromyricetin, by regulating the JNK/MMP-2 pathway, reverses EMT and suppresses cancer cell migration and invasion." (PMID 39906672, 2024). "MMP2, a matrix metalloproteinase, is directly involved in the breakdown of collagen and gelatin components of the ECM, facilitating cancer cell migration." (PMID 39598801, 2024). "TCM compounds such as curcumin and berberine can downregulate MMP-2 and MMP-9 expression, inhibiting cancer cell invasion and reducing metastasis." (PMID 39906672, 2024). "Among the different MMPs, MMP-2 (gelatinase A) and MMP-9 (gelatinase B) are notably significant in cancer metastasis due to their potential to degrade type IV collagen, a primary element of the basement membrane." (PMID 39431222, 2024). "In a proteome array analysis of 84 human cancer-related proteins we identified several proteins being solely expressed by the T18 stromal cells like cathepsin B, D and S, interleukins, EGFR and MMP-2 as well as progranulin, Axl and PAI-1." (PMID 39695086, 2024). "Expression of MMP2 and MMP9 is regulated by fatty acid-binding protein 5 (FABP5), a cancer metastasis promoting protein." (PMID 38215076, 2024). "The literature reveals that TNF-α, VEGF-α, COX-2, MMP-2, Caspase-3, and NOS are interconnected in various cancer processes." (PMID 38918540, 2024). "Plant-derived compounds, specifically polyphenols—the subject of this review—are suggested to play an important role in preventing cancer progression as MMP, especially MMP-2 and MMP-9, inhibitors." (PMID 39335164, 2024). "HOTAIR promotes matrix metalloproteinase (MMP‐2 and MMP‐9) activity for cell motility and the capacity to dissolve the basement membrane contributing to the invasion of cancer cells." (PMID 39725668, 2024). "MMPs, particularly MMP2 and MMP9, are crucial zinc‐dependent endopeptidases that facilitate cancer cell migration." (PMID 39415846, 2024). "Several research groups have proposed strategies for enhancing MMP inhibitors’ effectiveness, particularly MMP-2 and MMP-9, in cancer treatments." (PMID 39063556, 2024). "Those cancers with high expression of PDPN, MMP2 and THY1 were enriched for immune-mediated pathways, such as inflammatory response, IFN response, and IL6-JAK-STAT signaling." (PMID 39335130, 2024). "Among all MMPs, MMP-2 and MMP-9 are key to basement membrane type IV collagen degradation during cancer progression." (PMID 38539165, 2024). "MMP-2 and MMP-9, members of the matrix metalloproteinase family, play a vital role in various tumors and are considered key regulators of cancer progression." (PMID 38951593, 2024).
cancer (continued). "We designed and assembled a LIFU/MMP-2 dual-responsive and phase-changeable nanoplatform loaded with DSF for VM-based cancer therapy." (PMID 38664830, 2024). "MMP-2 and MMP-9, two important matrix metalloproteinases, have a significant impact on the invasion and metastasis of cancer cells." (PMID 38434979, 2024). "Elevated ECM stiffness activates the FAK/RhoA/ROCK and PI3K/AKT signaling pathways via integrins, thereby increasing the expression of MMP2 and MMP9, and enhancing the invasiveness of cancer cells." (PMID 38693104, 2024). "We primarily attribute this to its demonstrated cytotoxic effects on cancer cell lines, anti-inflammatory characteristics, antimetastatic properties, capacity to induce apoptosis, and ability to inhibit the JNK/SMAD4/MMP2 signaling pathway." (PMID 38773159, 2024). "MMPs, particularly MMP-2 and MMP-9, play crucial roles in cancer metastasis by degrading the extracellular matrix components, which facilitates invasion and further progression." (PMID 39203749, 2024). "The carcinogenic process is believed to involve MMP-2 and MMP-9 in order to angiogenesis and metastasis occurring in various cancer cell lines." (PMID 39497156, 2024). "Plasma levels of MMP-2 and MMP-9 were significantly elevated in the DMH-induced cancer group compared to the control group." (PMID 39858430, 2024). "RA’s anticancer properties have been demonstrated in in vitro, in vivo, and in silico models, particularly through the activation of apoptotic pathways and the inhibition of key enzymes, like MMP-2 and MMP-9, which are involved in cancer metastasis." (PMID 39594455, 2024). "Considerable evidence, research, and publications have indicated that MMPs, including MMP-2 and MMP-9, are actively involved in the spread of malignant cells in tumors by increasing cancer-cell growth, migration, invasion, and angiogenesis." (PMID 38893149, 2024). "MMPs, particularly MMP-2 and MMP-9, are key in governing cancer invasion and metastasis by degrading the ECM and promoting EMT." (PMID 38693104, 2024). "Given the specifically high level of MMP-2 where VM is prone to occur, the PEG shed in response to MMP-2 provides a great impetus for DSF uptake by specific cancer cells." (PMID 38664830, 2024). "Elevated levels of MMP-2 and MMP-9 are often used as biomarkers for the diagnosis and prognosis of various diseases, including cancer and cardiovascular diseases." (PMID 39858430, 2024). "Among them, integrin αVβ3 reportedly regulates proteolytic activity on cancer cell membranes as a plasma membrane receptor for active matrix metalloproteinase-2 (MMP-2), beyond acting as a cancer cell motility and promoter of angiogenic factor." (PMID 38312516, 2024). "MMP-2 and MMP-9 are two critical enzymes that mediate extracellular matrix (ECM) degradation, which is an important process that allows cancer cell invasion and metastasis." (PMID 38879516, 2024). "Studies have also shown the involvement of GH in elevating MMPs, particularly MMP2 and MMP9, thereby promoting cancer cell migration and invasion." (PMID 39123364, 2024). "Some of the most recent in vitro and in vivo studies investigating the effects of natural and synthetic polyphenols on the expression and activity of MMP-2 and MMP-9 in various cancer models are summarized below." (PMID 39335164, 2024). "The upregulation of RECK protein prevents the migration and invasion of cancer cells in hepatocellular carcinoma by downregulating the downstream protein STAT3 and matrix metalloproteinases like MMP2, MMP9, and MT1-MMP." (PMID 39456564, 2024). "qRT-PCR analysis displayed that the mRNA expression of MMP-2, MMP-3, MMP-7, and MMP-9 in the cervical tissue of patients with cancer was significantly greater than that in the control (p = 0.005, p < 0.001, p < 0.001, and p = 0.038, respectively)." (PMID 39247608, 2024). "We analyzed the expression of MMP-2 and MMP-9 on MDA-MB-231 cancer cells after treatment with DiMeOC-Mg-BCD (at CC50) for 48 h by RT-PCR." (PMID 38673967, 2024).